AFF4 (ALF transcription elongation factor 4)
Description:
Key component of the super elongation complex (SEC), a complex required to increase the catalytic rate of RNA polymerase II transcription by suppressing transient pausing by the polymerase at multiple sites along the DNA. In the SEC complex, AFF4 acts as a central scaffold that recruits other factors through direct interactions with ELL proteins (ELL, ELL2 or ELL3) and the P-TEFb complex. In case of infection by HIV-1 virus, the SEC complex is recruited by the viral Tat protein to stimulate viral gene expression.
Synonyms: AF5Q31; MCEF; CHOPS
Tractability: Small molecule: a structure with a bound ligand is known. PROTAC: UniProt records ubiquitination sites on it; ubiquitination databases record sites on it; its protein half-life has been measured.
Gene: Protein-coding gene on chromosome 5 (132,875,395 to 132,963,634, reverse strand). Ensembl gene ENSG00000072364.
Subcellular location: Nucleus; Chromosome
Subcellular location (Human Protein Atlas): Nucleoplasm; Nuclear bodies; Nucleoli fibrillar center
Pathways (Reactome):
Gene expression (Transcription): Formation of RNA Pol II elongation complex; RNA Polymerase II Pre-transcription Events; RNA Polymerase II Transcription Elongation
Gene Ontology:
Molecular function: protein binding; transcription coregulator activity
Biological process: DNA-templated transcription elongation; nervous system process; regulation of DNA-templated transcription; regulation of gene expression; response to endoplasmic reticulum stress
Cellular component: chromosome; fibrillar center; nuclear body; nucleoplasm; nucleus; transcription elongation factor complex; euchromatin; super elongation complex
Genetic constraint (gnomAD): Loss-of-function variants: 6 observed, 103.88 expected, observed/expected ratio (o/e) 0.0578, 90% interval 0.031 to 0.11. The upper end of that interval is the gene's LOEUF score, 0.11, which puts it in group 1 of 6, group 1 being the genes least tolerant of losing a copy. Missense variants: 1,000 observed, 1,369.9 expected, observed/expected ratio (o/e) 0.73, 90% interval 0.69 to 0.77. Synonymous variants: 447 observed, 490.24 expected, observed/expected ratio (o/e) 0.91, 90% interval 0.84 to 0.99.
Cancer hallmarks: invasion and metastasis (promotes); proliferative signalling (promotes)
Homologues: Orthologues: chimpanzee AFF4 (99% identical), macaque AFF4 (99% identical), dog AFF4 (97% identical), pig AFF4 (96% identical), rabbit AFF4 (96% identical), rat Aff4 (93% identical), mouse Aff4 (93% identical), guinea pig AFF4 (91% identical), tropical clawed frog aff4 (79% identical), zebrafish aff4 (58% identical), Drosophila melanogaster lilli (23% identical). Paralogues in human: AFF1 (39% identical), AFF2 (38% identical), AFF3 (36% identical).
Diseases named in the same sentence as AFF4 in open-access papers:
AFF4 is named in the same sentence as 56 diseases in open-access papers, as found by Europe PMC text mining. Sharing a sentence is not in itself a finding about the gene and the disease. The quoted sentences say what the papers report.
bladder cancer (14 papers, 2019 to 2024). "For example, METTL3 regulates SOX2 mRNA in glioma stem cell maintenance and colorectal tumor progression, LEF1 in osteosarcoma progression, AFF4/NF-kB/MYC in bladder cancer, and SPHK2 in gastric cancer." (PMID 36183833, 2022). "A recent study found that overexpression of m6A methyltransferase METTL3 facilitates tumor development through AFF4/NF-κB/MYC signal pathway in bladder cancer." (PMID 34367534, 2021). "For example, in bladder cancer, the m6A regulator METTL3 promotes the progression of bladder cancer through the AFF4/NF-kB/MYC signaling network." (PMID 33952279, 2021). "The ectopic expression of METTL3 potentiates bladder cancer progression through the AFF4/NF‐κB/MYC network." (PMID 33029866, 2020). "METTL3 promoted the proliferation and metastasis of bladder cancer via the AFF4/NF‐κB/MYC signalling network in an m6A‐dependent manner." (PMID 32808488, 2020). "As a main component in the so-called m6A ‘writer’, METTL3 was reported to have the ability to promote bladder cancer progression via AFF4/NF-κB/MYC signaling network by an m6A dependent manner." (PMID 31228940, 2019). "As such, the METTL3/AFF4/MYC axis contributes to bladder cancer tumorigenesis." (PMID 34185971, 2022). "Besides, AFF4 binds to the promoter of MYC, suggesting the METTL3/m6A/AFF4/NF-κB/MYC axis for bladder cancer tumorigenesis." (PMID 33099572, 2020). "In bladder cancer, METTL3 could promote the bladder cancer progression via AFF4/NF-κB/MYC signaling network by an m6A dependent manner." (PMID 31228940, 2019). "They further found that methyltransferase-like 3 (METTL3), an main component in the so-called m6A ‘writer’, could promote bladder cancer progression via AFF4/NF-κB/MYC signaling network by an m6A dependent manner." (PMID 31228940, 2019). "For instance, METTL3 is highly expressed and promotes bladder cancer by promoting the expressions of MYC and AFF4; inhibition of METTL3 reduces bladder tumor cell proliferation, migration, and invasion." (PMID 39457524, 2024). "METTL3 is significantly up-regulated and mediates AFF4-NF-κB-MYC signaling pathway, thus promoting the malignant biological behaviors of bladder cancer cells." (PMID 35022030, 2022). "In bladder cancer, the over-expression of METTL3 increases m6A methylation status, regulates the expression of AFF4, promotes its transcription by combining with the promoter region of Sox2, and promotes the self-renewal of cancer stem cells." (PMID 35022030, 2022). "Cheng et al31 found that the expression of METTL3 was elevated in bladder cancer and further identified AF4/FMR2 family member 4 (AFF4), key regulators of the NF‐κB pathway (IKBKB and RELA) and MYC as direct downstream targets of METTL3." (PMID 32808488, 2020). "AFF4 (AF4/FMR2), as a core component of the super elongation complex, is involved in the progression of cancer, e.g., leukemia, head and neck squamous cell carcinoma, melanoma, bladder cancer, and lung cancer." (PMID 34686190, 2021). "Similarly, in bladder cancer, the METTL3-mediated m6A modification on the AFF4 could promote its expression." (PMID 33099572, 2020).
leukemia (7 papers, 2017 to 2022). A malignant (clonal) hematologic disorder, involving hematopoietic stem cells and characterized by the presence of primitive or atypical myeloid or lymphoid cells in the bone marrow and the blood. "Secondly, AFF4 promotes malignancy`s initiation and progression in the reported diseases such as leukemia, head and neck cancer, and bladder tumor." (PMID 35223479, 2022). "AFF4 is required for MLL1-r leukemia, as its knockdown resulted in the decreased expression of MLL1 target genes." (PMID 33823889, 2021). "RNA-sequencing was performed to investigate how 1-mediated disruption of the PPIs between AF9/ENL and DOT1L or AF4/AFF4 affects global gene expression in MLL-r leukemia." (PMID 34373735, 2021). "Also, AFF4 promoted tumorigenesis and initiation, progression, invasion, and metastasis in leukemia, HIV transcription, and head and neck cancer." (PMID 35223479, 2022). "Depletion of AFF4 in leukemia cells results in reduced expression of MLL chimeric target genes." (PMID 35223479, 2022). "Further investigation using MLL1-AF4 and AFF4 with deletion of various AF4/AFF4 domains showed that only the CHD domain of AFF4/AF4 is required for leukemic transformation, while other AF4/AFF4′s interacting domains with P-TEFb, ELL and AF9/ENL are dispensable for MLL1-AF4/AFF4 leukemia." (PMID 33823889, 2021). "Therefore, targeting the PPIs between cyclin-T1 and AFF4/AF4 represents a potential therapeutic approach to the treatment of MLL1-r leukemia and HIV infection." (PMID 33823889, 2021). "Therefore, PPIs between AHD and DOT1L or AF4/AFF4 are a potential drug target for MLL-r leukemia." (PMID 34373735, 2021). "Despite > 70 fusion partners of MLL1 were identified, only a few are frequently found in ~ 70% MLL1-r leukemias, including transcription cofactors AF9 (also known as MLLT3) and its paralog ENL (also known as MLLT1), AF4 and its paralog AFF4, and ELL." (PMID 35395864, 2022). "Although there are > 70 documented fusion partners of MLL1, transcription cofactors AF4 (also known as AFF1) and its paralog AFF4, AF9 and its paralog ENL, and ELL are found in > 70% MLL1-r leukemias." (PMID 33823889, 2021). "Similarly, compound 1 dose-dependently reduced the nuclear levels of H3K79-Me1/2 and ENL in MLL-AF4 driven MV4;11 leukemia cells, while it did not cause significantly decreased AFF4 at 10 μM, presumably due to direct recruitment of AFF4 by MLL-AF4 through heterodimerization." (PMID 34373735, 2021). "Most frequent MLL1-fusion partners AF4/AFF4, AF9/ENL and ELL, together with CDK9/cyclin-T1, constitute super elongation complexes (SEC), which promote aberrant gene transcription, oncogenesis and maintenance of MLL1-rearranged (MLL1-r) leukemia." (PMID 35395864, 2022). "The AF4/AFF4-ELL interaction is a potential drug target for MLL1-ELL and/or other MLL1-r leukemia." (PMID 33823889, 2021).
CHOPS syndrome (5 papers, 2015 to 2025). "Missense mutation in human AFF4 gene leads to CHOPS syndrome that phenotypically overlaps Cornelia de Lange syndrome (CdLS)." (PMID 36149892, 2022). "This notion is further supported by the finding that mutations in AFF4 gene are associated with CHOPS syndrome which phenotypically overlaps CdLS48." (PMID 26581180, 2015). "Similarly, the microphthalmia phenotype in Aff4−/− E15.5 embryos is consistent with the higher incidence of eye anomalies and cataracts in patients with CHOPS syndrome many of whom also exhibit heterozygous mutations of the AFF4 gene." (PMID 36737727, 2023). "To date, AFF4 was discovered to be closely relevant to mixed lineage leukemia and CHOPS syndrome." (PMID 36149892, 2022).
head and neck squamous cell carcinoma (4 papers, 2020 to 2021). A squamous cell carcinoma that arises from any of the following anatomic sites: lip and oral cavity, nasal cavity, paranasal sinuses, pharynx, larynx, and salivary glands. "For instance, AFF4 could upregulate SOX2 transcription to promote the tumor-initiation capacity of head and neck squamous cell carcinoma (HNSCC), and MYC is another known target of AFF4." (PMID 32676121, 2020).
breast carcinoma (3 papers, 2009 to 2021). "They use a series of pull down assays, genetic backgrounds, and global sequencing analysis and show that AFF4 binds to H2K27ac at promoters and influences the ER alpha signaling and breast cancer cell growth." (PMID 32265480, 2020). "We knocked down AFF4 expression with siRNAs in two luminal A breast cancer cell lines, MCF7 and T47D." (PMID 32265480, 2020). "Due to the importance of ERα in breast cancer cell growth, we further examined the effect of AFF4 ablation on cell growth." (PMID 32265480, 2020). "We first examined the AFF4 mRNA levels in different breast cancer PAM50 subtypes based on the TCGA breast invasive carcinoma gene expression dataset." (PMID 32265480, 2020). "Depletion of AFF4 by siRNA or CRISPR/Cas9 dramatically reduces expression of ESR1 and its target genes, consequently inhibiting breast cancer cell growth." (PMID 32265480, 2020). "Depletion of AFF4 by CRISPR-Cas9 reduced the recruitment of transcriptional elongation factors and RNA polymerase II to the ESR1 transcription start sites, decreased ESR1 gene expression, and inhibited the growth of ER-positive breast cancer cells." (PMID 32265480, 2020).
lung carcinoma (3 papers, 2020 to 2026). "Further screening and validation revealed that circAFF4, a circular RNA derived from AFF4 host gene, also exhibited a similar trend in lung cancer." (PMID 42010438, 2026). "METHODS: Through retrieval from The Cancer Genome Atlas (TCGA) database, the differential expression of AFF4 mRNA in lung cancer was identified." (PMID 42010438, 2026).
melanoma (3 papers, 2021 to 2023). A malignant, usually aggressive tumor composed of atypical, neoplastic melanocytes. "AFF4 also facilitates melanoma progression by upregulating c-Jun transcriptional activity." (PMID 37063434, 2023). "AFF4 can promote the invasion and migration of melanoma cells by mediating EMT and c-Jun activity." (PMID 37221600, 2023).
Obesity (3 papers, 2017 to 2024). Accumulation of substantial excess body fat. "Gain-of-function mutations in AFF4, encoding a subunit of the SEC, result in the CdLS-related CHOPS (OMIM# 616368) (Cognitive development and coarse facies, Heart defects, Obesity, Pulmonary involvement, and Short stature and skeletal dysplasia) syndrome." (PMID 35615272, 2022). "De novo gain-of-function mutations in AFF4 were recently identified in three patients with a new syndrome, CHOPS (cognitive development and coarse facies, heart defects, obesity, pulmonary involvement, short stature, and skeletal dysplasia), that displays phenotypic overlap with CdLS." (PMID 28041881, 2017).
diffuse midline glioma (2 papers, 2022 to 2023). A diffuse glioma that arises from the midline structures of the central nervous system. "More recently, H3K27M oncohistone-expressing diffuse midline gliomas (DMGs) have been shown to deregulate the expression of AFF4, a scaffolding protein involved in transcriptional elongation, which CDK9/CyclinT regulates." (PMID 35567477, 2022).
acute leukemia (1 paper, 2023). A clonal (malignant) hematopoietic disorder with an acute onset, affecting the bone marrow and the peripheral blood. "MLL-AFF4 fusion gene has been discovered in acute leukemia, whether AFF4 alone plays a role in tumor, especially pancreatic tumorigenesis, is still elusive." (PMID 37063434, 2023).
acute lymphoblastic leukemia (1 paper, 2015). Leukemia with an acute onset, characterized by the presence of lymphoblasts in the bone marrow and the peripheral blood. "The AFF (AF4/FMR2) family of genes includes four members: AFF1 (or AF4, acute lymphoblastic leukemia-1 fused gene from chromosome 4), AFF2 (or FMR2, Fragile X mental retardation 2), AFF3 and AFF4 (or AF5Q31, acute lymphoblastic leukemia-fused gene from 5q31)." (PMID 26214578, 2015).
AIDS (1 paper, 2013). A syndrome resulting from the acquired deficiency of cellular immunity caused by the human immunodeficiency virus (HIV). "In addition to assisting with the expression of hundreds of human genes, super elongation complexes containing P-TEFb-AFF4 are hijacked in various forms of cancer and viral infections, including HIV/AIDS." (PMID 23471103, 2013).
breast invasive carcinoma (1 paper, 2020). "The correlation of ESR1 and AFF4 expression in the TCGA breast invasive carcinoma dataset with 971 completed tumors was calculated." (PMID 32265480, 2020).
breast tumors (1 paper, 2020). "AFF4 mRNA is highly expressed in luminal A, luminal B, and some Her2-positive tumors, but is absent in the basal subtype of breast tumors, suggesting that the expression of AFF4 and ESR1 has a positive correlation." (PMID 32265480, 2020).
colorectal cancer (1 paper, 2022). A primary or metastatic malignant neoplasm that affects the colon or rectum. "The final results confirmed that AFF4 deficiency enhanced the capacity of colorectal cancer cells to metastasize in vivo." (PMID 35223479, 2022). "Although there are numerous connections linking diseases with AFF4, however, whether colorectal cancer progression is associated with AFF4 expression remains unknown." (PMID 35223479, 2022). "However, the mechanism underlying the effects of AFF4 on colorectal cancer remains unclear." (PMID 35223479, 2022). "In conclusion, the present study displayed that AFF4 is downregulated in CRC tissues, which is inversely predicted with poor prognosis, revealing the key role of AFF4 in colorectal cancer." (PMID 35223479, 2022). "We found that AFF4 was significantly downregulated in colorectal cancer tissues and the prognosis of patients with low expression of AFF4 was poor." (PMID 35223479, 2022). "This research aimed to investigate the role of AFF4 on colorectal cancer by measuring proliferation, migration, as well as invasion capacity in vitro and in vivo." (PMID 35223479, 2022). "AFF4 depletion or amplification is associated with multiple cancers, but its role in colorectal cancer (CRC) has not been investigated so far." (PMID 35223479, 2022). "The results showed that AFF4 was significantly downregulated in colorectal cancer tissues." (PMID 35223479, 2022). "The results suggested that AFF4 may play an important role in colorectal cancer suppression." (PMID 35223479, 2022). "We firstly examined the expression of AFF4 in colorectal cancer and normal tissues by collecting paired CRC tissues and adjacent normal tissues, revealing that AFF4 was significantly downregulated in CRC patients and lower expression of AFF4 was correlated with poor prognosis." (PMID 35223479, 2022). "Interesting, the absence of AFF4 significantly promoted the migration and invasion of HT29 and DLD-1 cells after 24 h, suggesting that AFF4 may have the function of suppressing colorectal cancer metastasis." (PMID 35223479, 2022).
diabetes (1 paper, 2022). "Further study illustrating the regulation of AFF4 on adipose lipid and energy metabolism, and related diseases like diabetes, is warranted." (PMID 36149892, 2022).
glioblastoma (1 paper, 2019). The most malignant astrocytic tumor (WHO grade IV). "GST-PTEN also interacted with endogenous AFF4 from PTEN-deficient DBTRG-05MG glioblastoma and HEK293 cell lysates, indicating that PTEN can bind to a component of the transcription machinery." (PMID 31169889, 2019).
HIV-1 infection (1 paper, 2024). The type species of lentivirus and the etiologic agent of acquired immunodeficiency syndrome (AIDS). "However, knock-out of the other SEC components either did not alter HIV-1 infection (AFF4, ELL2, AF9) or resulted in a very slight, but statistically significant increase in infection (AFF1, ENL)." (PMID 39259751, 2024).
keloid (1 paper, 2022). An irregularly shaped, elevated mark on the skin caused by deposits of excessive amounts of collagen during wound healing. "In conclusion, expression levels of hsa_circ_0057452 and AFF4 were found to be upregulated in keloids, while those of miR-1225-3p were downregulated." (PMID 35706403, 2022). "The levels of hsa_circ_0057452, microRNA (miR)-1225-3p, and AF4/FMR2 family member 4 (AFF4) in keloid tissues and keloid fibroblasts (KFs) were determined using quantitative reverse transcription-polymerase chain reaction." (PMID 35706403, 2022). "This study aimed to investigate the functional role of hsa_circ_0057452 in keloid growth and clarify the key role of the hsa_circ_0057452/miR-1225-3p/AFF4 axis in the growth regulation of KFs." (PMID 35706403, 2022). "We found that hsa_circ_0057452 and AFF4 expression levels were upregulated, whereas miR-1225-3p expression levels were downregulated in keloids." (PMID 35706403, 2022). "Therefore, our results show that hsa_circ_0057452 promotes keloid progression by targeting miR-1225-3p and regulating AFF4 levels." (PMID 35706403, 2022). "Moreover, there is a lack of animal models to study the effects of the hsa_circ_0057452/miR-1225-3p/AFF4 axis on keloids in vivo." (PMID 35706403, 2022). "AFF4 levels were found to be significantly elevated in keloids." (PMID 35706403, 2022). "Moreover, hsa_circ_0057452 adsorbed miR-1225-3p to further upregulate AFF4 expression levels to facilitate keloid progression." (PMID 35706403, 2022). "In addition, mechanical function experiments showed that AFF4 acted on keloid genesis and development via targeted inhibition by miR-1225-3p." (PMID 35706403, 2022).
microphthalmia (1 paper, 2023). Congenital or developmental anomaly in which the eyeballs are abnormally small. "A similar search of DR17 using the term microphthalmia resulted in 22 genes significant for the small eyes phenotype: Aldh1a3, Aff4, Bmp4, Cdk4, Cox6b1, Cxcr4, Dync1li1, Eef1d, Fgd1, Gne, Grh12, Mab21l2, Maf, Med13l, Mllt10, Mthfd2, Pex6, Phgdh, Ssr1, Stim1, Tdo2, and Vps26c." (PMID 36737727, 2023).